ENDOG (endonuclease G)
Diseases named in the same sentence as ENDOG in open-access papers (continued):
Sharing a sentence is not in itself a finding about the gene and the disease.
neurodegenerative disease (4 papers, 2016 to 2024). A disorder of the central nervous system characterized by gradual and progressive loss of neural tissue and neurologic function. "Given the known roles of ENDOG in the DDR and the emerging link between DDR linked to mitochondrial dysfunction and neurodegenerative diseases, these findings may therefore prove to be of future clinical importance." (PMID 38227585, 2024).
mitochondrial disease (1 paper, 2022). "The presence of multiple mtDNA deletions supports the role of ENDOG in mtDNA maintenance; moreover, the patient’s clinical presentation is very similar to mitochondrial diseases caused by mutations in other genes involved in mtDNA homeostasis." (PMID 35326425, 2022). "In conclusion, we identified biallelic variants in ENDOG, a gene that has not been previously associated with any mitochondrial disease." (PMID 35326425, 2022).
ENDOG also shares sentences with these, for which no sentence is quoted: leukemia (2 papers); adenomyosis (1); alcohol addiction (1); asthma (1); chondrosarcoma (1); colorectal adenocarcinoma (1); diabetes (1); endometrioid tumor (1); External ophthalmoplegia (1); follicular thyroid carcinoma (1); head and neck cancer (1); heart failure (1); infertile (1); lymphocyte tumor (1); neuroblastoma (1); osteosarcoma (1); Parkinson disease (1); prostate carcinoma (1); schizophrenia (1); Stroke (1); thyroid anaplastic carcinoma (1).